HSPA1B (heat shock protein family A (Hsp70) member 1B)
Diseases named in the same sentence as HSPA1B in open-access papers (continued):
Sharing a sentence is not in itself a finding about the gene and the disease.
breast tumor (1 paper, 2022). "We therefore next examined the co-expression correlation between HSPs and co-chaperones including HSP90 family (HSP90AA1, HSP90AB1), HSP70 family (HSPA1A, HSPA1B, HSPA8) and BAG family (BAG1, BAG2, BAG3) among 960 breast tumor samples registered in the Cancer Genome Atlas (TCGA)." (PMID 36114410, 2022).
chronic obstructive pulmonary disease (1 paper, 2022). A chronic and progressive lung disorder characterized by the loss of elasticity of the bronchial tree and the air sacs, destruction of the air sacs wall, thickening of the bronchial wall, and mucous accumulation in the bronchial tree. "In a closely related respiratory disorder, chronic obstructive pulmonary disease (COPD), HSPA1B rs2763979 (CT + TT) was associated with disease susceptibility together with another promoter SNP (rs6457452), highlighting their possible implication in chronic respiratory diseases susceptibility." (PMID 36553658, 2022).
colitis (1 paper, 2017). Inflammation of the colon. "In mice, Hspa1a and Hspa1b double knockout mice were phenotypically normal; however, when treated with dextran sulfate sodium and exposed to oxidative stress, they exhibited colitis." (PMID 28126021, 2017).
Crohn disease (1 paper, 2024). A gastrointestinal disorder characterized by chronic inflammation involving all layers of the intestinal wall, noncaseating granulomas affecting the intestinal wall and regional lymph nodes, and transmural fibrosis. "We painted the landscapes of monocyte-macrophages and identified 5 distinct subsets including monocytes, C1QB+ macrophages, HSPA1B+ macrophages, IL-1B+ macrophages, and TMSB4X + macrophages in the intestinal mucosa from Crohn’s disease patients." (PMID 39095853, 2024).
E. coli infection (1 paper, 2023). "Based on DEGs, WGCNA, and MCODE, key genes associated with E. coli infection were discovered, including CXCL3, HSPA1B, TNF, and PLPP3." (PMID 38066783, 2023). "In differentiating E. coli infection from other bacterial infections, the AUC values of IL2 were 0.5846, HSPA1B was 0.7038, TNF was 0.7116, and the combined value of the three was 0.71." (PMID 38066783, 2023). "In differentiating healthy and E. coli infection groups, the AUC values of IL2 were 0.7299, HSPA1B was 0.7931, TNF was 0.8218, and the combination of the three was 0.8793." (PMID 38066783, 2023). "In the validation set, compared to the other bacterial infection groups, we discovered that the E. coli infection group had a greater TNF level (p < 0.05), while the HSPA1B level was diminished in comparison to the other bacterial groups (p < 0.01)." (PMID 38066783, 2023). "The study suggested that HSPA1B and TNF may be E.-coli-infection-specific genes, which may help explain the molecular mechanism of infectious sepsis." (PMID 38066783, 2023).
enterocolitis (1 paper, 2025). An inflammatory process affecting the small intestine and colon. "Moreover, we detected the decreased levels of PRDX2, HSPA1B, and catalase, suggesting a diminished antioxidative capacity in NEC, which was consistent with previous studies on necrotizing colitis or enterocolitis." (PMID 39562369, 2025).
esophageal cancer (1 paper, 2021). A primary or metastatic malignant neoplasm involving the esophagus. "HSPA1B could be considered as a promising target for prognostic prediction in esophageal cancer." (PMID 33960364, 2021).
glioblastoma (1 paper, 2018). The most malignant astrocytic tumor (WHO grade IV). "HSPA1B is highly expressed in glioblastoma and is related to the pharmacological effects of erlotinib." (PMID 30322114, 2018). "Rule 11 involves four functional genes, indicating that high expression of HSPA1B and MARCKS, together with the low expression of RPSAP58 and PRDX1, may indicate that a patient may suffer from glioblastoma." (PMID 30322114, 2018).
glioma (1 paper, 2020). A benign or malignant brain and spinal cord tumor that arises from glial cells (astrocytes, oligodendrocytes, ependymal cells). "The mRNA expression of CANX, HSPA1B, PSMC6, and TAP1 was high in gliomas, whereas that of KLRC2 was low." (PMID 32351547, 2020).
gout (1 paper, 2022). A condition characterized by painful swelling of the joints, which is caused by deposition of urate crystals. "We found bisacumol, campesterol, and stigmasterol to be the main turmeric compounds that exerted a marked effect on gout treatment by targeting protein processing in the endoplasmic reticulum through the HSPA1B, HSP90AB1, and STUB1 proteins." (PMID 36276864, 2022). "Our PPI analysis showed that turmeric and corn silk influence gout through their impact on a complex biological network, including HSPA1B, HSP90AB1, STUB1, CTNNB1, YWHAG, and YWHAZ." (PMID 36276864, 2022). "Candidate targets of turmeric for gout were HSPA8, VCP, HSP90AB1, HSPA5, HSPA1B, NFKB1, and STUB1." (PMID 36276864, 2022). "These active ingredients may target protein processing in the endoplasmic reticulum through HSPA1B, HSP90AB1, and STUB1 proteins and play a significant role in treating gout." (PMID 36276864, 2022).
Huntington disease (1 paper, 2012). Huntington disease (HD) is a rare neurodegenerative disorder of the central nervous system characterized by unwanted choreatic movements, behavioral and psychiatric disturbances and dementia. "Some altered proteins are even more specifically linked to pathology of Huntington's disease, such as Heat shock protein-70 (Hspa1b), cytoplasmic dynein 1 heavy chain 1 (Dync1h1)." (PMID 23094041, 2012).
leishmaniasis (1 paper, 2024). Infectious disease that is transmitted through the bite of hematophagous female phlebotomine sand flies. "Through PPI network analysis, hub genes such as Lcn2, Ltf, Mpo, Dnaja1, Hspa1a, Hspa1b and Hsph1 were screened out and might play important roles in the process of undernutrition promoting leishmaniasis." (PMID 38185681, 2024).
leukemia (1 paper, 2024). A malignant (clonal) hematologic disorder, involving hematopoietic stem cells and characterized by the presence of primitive or atypical myeloid or lymphoid cells in the bone marrow and the blood. "In contrast to solid tumors, the data presented herein suggest an inhibitory role for HSPA1B in leukemia progression, whose expression depend upon the level of UBASH3A and UBASH3B." (PMID 38461240, 2024). "Knockdown of HSPA1B in leukemia cells accelerated leukemogenesis indicating a role for these genes as negative regulators of leukemic cell growth." (PMID 38461240, 2024).
liver cancer (1 paper, 2022). An epithelial or non-epithelial malignant neoplasm that arises from the liver. "HBV can enhance the expression of activating transcription factor 7 (ATF7) by downregulating miR-340-5p, which in turn interacts with heat shock protein family A member 1B (HSPA1B), promoting cell proliferation and inhibiting apoptosis, which in turn affects the development of liver cancer." (PMID 36278230, 2022).
medulloblastoma (1 paper, 2023). A malignant, invasive embryonal neoplasm arising from the cerebellum. "HSPA1B changes 4–5-fold for medulloblastoma Daoy and neuroblastoma SH-SY5Y and around 13-fold for differentiated SH-SY5Y cells." (PMID 36979108, 2023).
memory impairment (1 paper, 2024). "It was reported that Hspa1b protects against Aβ42-induced memory impairments in a Drosophila model of AD41." (PMID 38734693, 2024).
metabolic syndrome (1 paper, 2024). A cluster of metabolic risk factors for CARDIOVASCULAR DISEASES and TYPE 2 DIABETES MELLITUS. "Using in silico data analysis, we created an mRNA-miRNA panel (ZBP1, HSPA1B, MAPK3 & mir-5192) associated with pancreatic cell dysfunction and metabolic syndrome and involved in necroptosis-related TNF pathway." (PMID 38961451, 2024).
metastatic disease (1 paper, 2021). "HSPA1A and HSPA1B were upregulated, while HSPA8 was downregulated in patients with metastatic disease." (PMID 34765552, 2021).
non-alcoholic steatohepatitis (1 paper, 2024). "Single-cell analysis of the GSE129516 dataset and expression profiling GSE184019 dataset analysis revealed that HSPA1B expression is elevated in non-alcoholic steatohepatitis (NASH)." (PMID 38786053, 2024).
Pneumocystis infection (1 paper, 2010). "Among the genes that were affected by dexamethasone and further affected by Pneumocystis infection, Mgst1 and Hspa1b genes were down-regulated, while Cd14, Irf8, Il1b, Cxcl13, Cxcr4, Fn1, Irf1, Cd74, S100a9, and Spp1 genes were up-regulated in all four groups." (PMID 20377877, 2010).
psoriasis (1 paper, 2025). An autoimmune condition characterized by red, well-delineated plaques with silvery scales that are usually on the extensor surfaces and scalp. "P. clypearia may ameliorate inflammation in psoriasis mice by modulating genes such as Hspa1a, Hspa1b, mt-Nd4l, mt-Nd5, mt-Nd6, Bcl2, Asns, Trib3, and associated pathways related to energy metabolism, cell growth, and apoptosis." (PMID 41385507, 2025). "The results indicated that P. clypearia may affect the energy metabolism, cell growth and apoptosis by regulating genes such as Hspa1a, Hspa1b, mt-Nd4l, mt-Nd5, mt-Nd6, Bcl-2, Asns, Trib3, GzmA, CTSG, etc, thereby mitigating psoriasis-related inflammation." (PMID 41385507, 2025).
psychosis (1 paper, 2023). "Hspa1b haplotypes are associated with improved positive and negative symptoms in inpatients and, recently, Hspa1b s1061581 genotypes were associated with improved treatment responses in first-episode psychosis." (PMID 37834084, 2023).
pulmonary fibrosis (1 paper, 2022). Chronic progressive interstitial lung disorder characterized by the replacement of the lung tissue by connective tissue, leading to progressive dyspnea, respiratory failure, or right heart failure. "Next, we examined the gene and protein expression of Rfx2, one of three common upregulated genes among the three combinations of nintedanib- and vehicle-treated mice based on progression of pulmonary fibrosis (Rfx2, Hspa1a, and Hspa1b), and Bmpr2." (PMID 35714115, 2022). "In the present study, fewer upregulated genes than downregulated genes were detected, and among the 3 combinations of nintedanib- and vehicle-treated mice based on the progression of pulmonary fibrosis, only three common upregulated genes were identified (Rfx2, Hspa1a, and Hspa1b)." (PMID 35714115, 2022).
pulmonary TB (1 paper, 2026). "Upregulated proteins in HSP macrophages included those encoding for Hsp70 family proteins (e.g., HSPA1A, HSPA1B, HSPA6, and HSPA8), which are known to modulate NF-κB–mediated release of pro-inflammatory cytokines from alveolar macrophages in pulmonary TB." (PMID 41489684, 2026).
skin cutaneous melanoma (1 paper, 2024). "HSPA1B, a prognostic biomarker in skin cutaneous melanoma, influences the regulation of the immune response to melanoma cancer cells." (PMID 39763976, 2024).
small cell lung carcinoma (1 paper, 2022). Small cell lung cancer (SCLC) is a highly aggressive malignant neoplasm, accounting for 10-15% of lung cancer cases, characterized byrapid growth, and early metastasis. "The precise mechanism by which the genotype influences the expression of HSPA1B was not studied; however, the homozygous genotype GG has been reported to be associated with reduced HSPA1B expression and was a negative predictor of survival in patients with small-cell lung cancer." (PMID 36291674, 2022).
systolic heart failure (1 paper, 2017). Heart failure caused by abnormal myocardial contraction during systole leading to defective cardiac emptying. "Our disease ontology analysis comparing HF-diet-induced, H3K4me3-occupied gene promoters with those of the control group linked Hsp1a1 and Hspa1b activation with severe disease progression in systolic heart failure and CVD." (PMID 28425976, 2017).
triple-negative breast carcinoma (1 paper, 2022). An invasive breast carcinoma which is negative for expression of estrogen receptor (ER), progesterone receptor (PR), and human epidermal growth factor receptor 2 (HER2). "In this study, freshly isolated triple-negative breast cancer biopsied cells obtained from consenting patients were subjected to flow cytometry and bioinformatic analysis to identify three endothelial cell subclusters: EC (ATP1B3), EC (HSPA1B), and EC (KRT7) in the tumor microenvironment." (PMID 35265720, 2022).
varicocele (1 paper, 2024). A condition characterized by the dilated tortuous veins of the spermatic cord with a marked left-sided predominance. "The increase in HSPA1B appears to be a defense mechanism against varicocele-induced oxidative stress damage." (PMID 39063558, 2024). "Therefore, in a patient with varicocele, HSPA1B was higher than in the control group." (PMID 39063558, 2024).
vascular dementia (1 paper, 2025). A degenerative vascular disorder affecting the brain. "Based on these results, HSP90AA1, HSPA1B, and DNAJB1 show considerable potential as diagnostic and therapeutic targets for vascular dementia, offering crucial molecular-level support for clinical diagnosis and subsequent treatment strategy formulation in VaD." (PMID 40808948, 2025). "This study, through the integration of multi-omics data and cross-validation with machine learning algorithms, systematically elucidates the pivotal regulatory roles and diagnostic value of heat shock protein family members HSP90AA1, HSPA1B, and DNAJB1 in vascular dementia (VaD)." (PMID 40808948, 2025). "This study integrates multi-omics data and machine learning to elucidate the immune-neurovascular regulatory roles of HSP90AA1, HSPA1B, and DNAJB1 in vascular dementia (VaD), supporting the core hypothesis that protein homeostasis imbalance drives VaD-related neuroinflammation." (PMID 40808948, 2025).
tumor (39 papers, 2011 to 2026). "Responders (CR/PR) exhibited robust cytotoxic T-cell activation characterized by up-regulation of GNLY, GZMB, and CXCL13, whereas non-responders (SD) uniquely showed persistent overexpression of HSPA1B, a stress-response gene associated with tumor progression and immune suppression." (PMID 42158872, 2026). "HSPA1B may be associated with remodeling of the tumor ecological niche in HCC." (PMID 37333982, 2023). "To assess the clinical relevance of NRF2 pathway activation in OAC primary tumours, we employed four NRF2 targets (KIAA0319, ARID3A, HSPA1B, PTGR1) from clusters 2 and 9 to calculate the risk score based on datasets from The Cancer Genome Atlas (TCGA)." (PMID 40473905, 2025). "We found that the CCL5 ligand secreted by BTG1+RGS1+ Tcm and HSPA1B+ Tcm cells bound to the SDC4/1 receptor on the surfaces of tumor cells." (PMID 37333982, 2023). "The heat-shock genes HSPA1A and HSPA1B show down-regulation in tumor and up-regulation in the periphery, and act as marker genes for neuron clusters." (PMID 35327982, 2022). "In contrast, non-responders (SD) exhibited persistent overexpression of HSPA1B, a stress-response gene linked to tumor progression and immune suppression." (PMID 42158872, 2026). "Moreover, overexpression of FLI1 in K562 (K562-fli1) cells resulted in downregulation of HSPA1B suggesting a tumor suppressor role for this gene." (PMID 38461240, 2024). "Tumor NK cells expressed similar DEGs to tumor T cells and were enriched for genes associated with protein folding and cytokine expression, including genes coding for heat shock proteins HSPA6, HSPA1B, and HSPA1A, and IFNG, a common cytotoxic marker." (PMID 35534852, 2022). "Hsp70s, including HSPA8, HSPA2, and HSPA1B, could be either tumor-promoting or tumor-suppressing depending on cell identity and context." (PMID 36120453, 2022). "Besides, the high HSPA1A, HSPA1B, HSPA4, HSPA5, HSPA8, HSPA13, and HSPA14 expressions were inversely associated with the overall survival rate of patients, tumor grade, and cancer stage." (PMID 34059060, 2021). "Indeed, inducible members of the HSP gene family, namely heat shock 70 kDa protein 6 (HSPA6) followed in rank by HSPA1A and HSPA1B were the most dominantly induced genes 4 h after PDT in the human tumor cell lines." (PMID 21738796, 2011). "Notably, we found that the direction of activation and differentiation of infiltrating T cells in HER2 + IBC tumours was associated mainly with the NF-KB signalling pathway, which is characterized by high expression of heat shock protein-related molecules (HSPA1A, HSPA1B)." (PMID 40624675, 2025). "Among these upregulated genes, Dennd4a, Nfil3, Hspa1b, Chac1, Ddit4, Mex3b, Lysmd3, and Zbtb10 are mainly involved in oxidative stress and inflammation response, whereas Plcxd2, Dusp1, Cep85l, and Dusp8 are generally considered as tumor‐suppressor genes by inhibiting proliferation of cancer cells." (PMID 40231790, 2025). "In addition, the HSPA1B+ Tcm subpopulation was significantly enriched in the HCC group, and HSPA1B was significantly enriched in all cell types in the HCC group, suggesting its association with the remodeling of the tumor ecological niche in HCC." (PMID 37333982, 2023). "The expression of heat-shock protein-related genes such as HSPA6,HSPA1B, and HSPA1A equips this macrophage subset to cope with the stressful tumor microenvironment and play a role in immune regulation." (PMID 41394809, 2025). "Heat shock proteins, particularly HSPA8 (found in both patient groups), as well as HSPA1B and HSPA1L, were found in LRPCa, reflecting the role of the HSP70 family in tumor cell survival." (PMID 40136513, 2025).